RBX1 (ring-box 1)
Description:
E3 ubiquitin ligase component of multiple cullin-RING-based E3 ubiquitin-protein ligase (CRLs) complexes which mediate the ubiquitination and subsequent proteasomal degradation of target proteins, including proteins involved in cell cycle progression, signal transduction, transcription and transcription-coupled nucleotide excision repair. CRLs complexes and ARIH1 collaborate in tandem to mediate ubiquitination of target proteins, ARIH1 mediating addition of the first ubiquitin on CRLs targets. The functional specificity of the E3 ubiquitin-protein ligase complexes depends on the variable substrate recognition components. As a component of the CSA complex mediates ubiquitination of Pol II subunit POLR2A at 'Lys-1268', a critical TC-NER checkpoint. Core component of the Cul7-RING(FBXW8) ubiquitin ligase complex, which mediates the ubiquitination and subsequent proteasomal degradation of target proteins. Recruits the E2 ubiquitin-conjugating enzyme CDC34 to the complex and brings it into close proximity to the substrate. Probably also stimulates CDC34 autoubiquitination. May be required for histone H3 and histone H4 ubiquitination in response to ultraviolet and for subsequent DNA repair. Promotes the neddylation of CUL1, CUL2, CUL4 and CUL4 via its interaction with UBE2M. Involved in the ubiquitination of KEAP1, ENC1 and KLHL41. In concert with ATF2 and CUL3, promotes degradation of KAT5 thereby attenuating its ability to acetylate and activate ATM. As part of a multisubunit complex composed of elongin BC complex (ELOB and ELOC), elongin A/ELOA, RBX1 and CUL5; polyubiquitinates monoubiquitinated POLR2A.
Synonyms: ROC1; RNF75; BA554C12.1
Tractability: Small molecule: an approved drug acts on it; a structure with a bound ligand is known; it has a high-quality binding pocket. PROTAC: ubiquitination databases record sites on it; its protein half-life has been measured.
Target class: Enzyme; Aminoacyltransferase
Safety:
Unwanted effects reported when the protein is acted on. In parentheses: how it was acted on, where the effect was seen, and who reports it.
neutropenia (source: ClinPGx)
Gene: Protein-coding gene on chromosome 22 (40,951,277 to 40,973,539, forward strand). Ensembl gene ENSG00000100387.
Subcellular location: Cytoplasm; Nucleus
Subcellular location (Human Protein Atlas): Nucleoplasm
Pathways (Reactome):
Signal Transduction: Degradation of DVL; Degradation of GLI1 by the proteasome; Degradation of GLI2 by the proteasome; Degradation of beta-catenin by the destruction complex; GLI3 is processed to GLI3R by the proteasome; Hedgehog 'on' state; NOTCH1 Intracellular Domain Regulates Transcription; Negative regulation of NOTCH4 signaling; Regulation of RAS by GAPs
DNA Repair: DNA Damage Recognition in GG-NER; Dual Incision in GG-NER; Dual incision in TC-NER; Formation of Incision Complex in GG-NER; Formation of TC-NER Pre-Incision Complex; Gap-filling DNA repair synthesis and ligation in TC-NER; Recognition of DNA damage by PCNA-containing replication complex; Transcription-Coupled Nucleotide Excision Repair (TC-NER)
Disease: Constitutive Signaling by NOTCH1 HD+PEST Domain Mutants; Constitutive Signaling by NOTCH1 PEST Domain Mutants; Evasion by RSV of host interferon responses; Loss of Function of FBXW7 in Cancer and NOTCH1 Signaling; Nuclear events stimulated by ALK signaling in cancer; Potential therapeutics for SARS; Vif-mediated degradation of APOBEC3G
Immune System: Antigen processing: Ubiquitination & Proteasome degradation; GSK3B-mediated proteasomal degradation of PD-L1(CD274); Interleukin-1 signaling; Prolactin receptor signaling; SPOP-mediated proteasomal degradation of PD-L1(CD274)
Cellular responses to stimuli: GSK3B and BTRC:CUL1-mediated-degradation of NFE2L2; KEAP1-NFE2L2 pathway; Oxygen-dependent proline hydroxylation of Hypoxia-inducible Factor Alpha; Regulation of BACH1 activity
Cell Cycle: FBXL7 down-regulates AURKA during mitotic entry and in early mitosis; Ubiquitin-Mediated Degradation of Phosphorylated Cdc25A
Metabolism of proteins: Neddylation; Ribosome Quality Control (RQC) complex extracts and degrades nascent peptide
Circadian clock: Degradation of CRY and PER proteins
DNA Replication: Orc1 removal from chromatin
Developmental Biology: Regulation of expression of SLITs and ROBOs
and 1 more pathways
Gene Ontology:
Molecular function: cullin family protein binding; molecular adaptor activity; NEDD8 ligase activity; protein binding; RNA polymerase II-specific DNA-binding transcription factor binding; ubiquitin protein ligase activity; ubiquitin protein ligase binding; ubiquitin-protein transferase activity; ubiquitin-ubiquitin ligase activity; NEDD8 transferase activity; zinc ion binding
Biological process: cellular response to amino acid stimulus; cellular response to oxidative stress; cellular response to UV; DNA damage response; negative regulation of canonical NF-kappaB signal transduction; negative regulation of insulin receptor signaling pathway; negative regulation of response to oxidative stress; negative regulation of type I interferon production; positive regulation of canonical NF-kappaB signal transduction; positive regulation of cilium assembly; positive regulation of proteasomal ubiquitin-dependent protein catabolic process; positive regulation of protein autoubiquitination; positive regulation of protein catabolic process; positive regulation of TORC1 signaling; proteasome-mediated ubiquitin-dependent protein catabolic process; protein K27-linked ubiquitination; protein K48-linked ubiquitination; protein K63-linked ubiquitination; protein monoubiquitination; protein neddylation; protein polyubiquitination; protein ubiquitination; RNA polymerase II transcription initiation surveillance; SCF-dependent proteasomal ubiquitin-dependent protein catabolic process; signal transduction in response to DNA damage; and 51 more
Cellular component: Cul2-RING ubiquitin ligase complex; Cul3-RING ubiquitin ligase complex; Cul4-RING E3 ubiquitin ligase complex; Cul4A-RING E3 ubiquitin ligase complex; Cul4B-RING E3 ubiquitin ligase complex; Cul5-RING ubiquitin ligase complex; Cul7-RING ubiquitin ligase complex; cullin-RING ubiquitin ligase complex; cytoplasm; Golgi apparatus; nucleoplasm; nucleotide-excision repair complex; nucleus; SCF ubiquitin ligase complex; site of DNA damage; centrosome; cytosol
Genetic constraint (gnomAD): Loss-of-function variants: 0 observed, 2.22 expected, observed/expected ratio (o/e) 0, 90% interval 0 to 1.26. That is too few expected variants to judge how well the gene tolerates losing a copy. Missense variants: 31 observed, 44.01 expected, observed/expected ratio (o/e) 0.7, 90% interval 0.53 to 0.95. Synonymous variants: 16 observed, 16.34 expected, observed/expected ratio (o/e) 0.98, 90% interval 0.66 to 1.49.
Homologues: Orthologues: chimpanzee RBX1 (100% identical), dog RBX1 (100% identical), guinea pig RBX1 (100% identical), macaque RBX1 (100% identical), mouse Rbx1 (100% identical), pig RBX1 (100% identical), zebrafish rbx1 (98% identical), Drosophila melanogaster Roc1a (85% identical), Caenorhabditis elegans rbx-1 (81% identical), tropical clawed frog rbx1 (81% identical), rat Rbx1 (77% identical). Paralogues in human: RNF7 (48% identical), ANAPC11 (31% identical).
Diseases named in the same sentence as RBX1 in open-access papers:
RBX1 is named in the same sentence as 73 diseases in open-access papers, as found by Europe PMC text mining. Sharing a sentence is not in itself a finding about the gene and the disease. The quoted sentences say what the papers report.
lung carcinoma (15 papers, 2014 to 2023). "For example, hsa-miR-1827 has been reported to be downregulated in highly invasive lung cancer sub-cell lines, and the overexpression of miR-1827 inhibits lung cancer cell migration via targeting RBX1 and CRKL." (PMID 36111773, 2023). "Our previous study using immune‐histochemical staining with limited samples showed that RBX1 is overexpressed in lung cancer tissues." (PMID 37470067, 2023). "We have enumerated three tumors of the highest incidence (breast, colorectal and lung cancer) to perform comprehensive prognosis analysis with RBX1/2 expression by the PrognoScan database." (PMID 36059474, 2022). "Except for the expression of RBX1 in lung cancer and RBX2 in COAD, the experimental results are basically consistent with the bioinformatics analysis." (PMID 36059474, 2022). "RBX1/2 were overexpressed in a number of primary cancer tissues, including carcinoma of lung, liver, breast, colon, and renal." (PMID 36059474, 2022). "The endogenous binding of these E2–E3 pairs was further confirmed in two lung cancer cell lines under physiological unstressed conditions in a pull-down assay using antibody against either SAG or RBX1 or antibodies against each of four E2s." (PMID 27910872, 2016). "We next determined the effect of transfected SAG/CUL5 or RBX1/CUL1 on endogenous levels of β-TrCP1 in two lung cancer cell lines, A427 and A549 harboring relatively high levels of β-TrCP1." (PMID 27910872, 2016). "Furthermore, using the in vitro cell culture models, we found that RBX1 was overexpressed in lung tumor cell lines, and RBX1 knockdown suppressed the growth of lung cancer cells by triggering apoptosis, G2/M arrest, DNA damage and senescence." (PMID 37470067, 2023). "Non‐small cell lung cancer (NSCLC), which accounts for ~ 80–85% of all lung cancer cases, exhibits mutations, or copy number alterations in NFE2L2/NRF2 or its degradation machinery (KEAP1, CUL3, or RBX1) in > 30% of NSCLC cell lines and patient tissues." (PMID 35184380, 2022). "Previous studies pointed out that RBX1 expression could regulate the tumor suppressor degradation in liver cancer and be a prognostic factor in lung cancer." (PMID 33931024, 2021). "While overexpression of SAG, but not of RBX1, is associated with poor survival of lung cancer patients, SAG expression is required to lung tumorigenesis triggered by Kras mutation." (PMID 27955654, 2016). "Thus, RBX1 appears to be a growth essential gene in prolifcation and survival of lung cancer cells." (PMID 37470067, 2023). "Our result showed that RBX1/2 reflected their characteristics respectively in the observation indicators mentioned, for example, RBX2 expression is more differentially expressed than RBX1 in LUSC, which may be one of the reasons that only RBX2 expression is associated with lung cancer prognosis." (PMID 36059474, 2022). "However, two other studies found that only RBX2 overexpression was correlated with the poor prognosis in lung cancer; as well as high RBX1 expression was related to poor survival only in KIRC patients and high RBX2 expression had a close relation with poor prognosis in all three types of RCC." (PMID 36059474, 2022). "RBX1 is overexpressed in many primary tumours, including liver cancer, non-musculoinvasive transitional cell carcinoma of the bladder (NMIBC), and lung cancer." (PMID 35802537, 2022). "In several primary tumors, including lung cancer, non-muscle invasive bladder transitional cell carcinoma (NMIBC), and liver cancer, RBX1 is overexpressed." (PMID 36810109, 2023). "We first determined potential correlation in the protein levels between SAG and NEDD4-1 in multiple human lung cancer cell lines, and found that the level of SAG, but not its family member RBX1, is largely correlated in a inverse manner with NEDD4-1." (PMID 25216516, 2014).
lung carcinoma (continued). "Using CENP-F as a G2/M cell marker, we observed a strongly negative correlation between the expression levels of RBX1 and EXO1 proteins in multiple cell types, including human cervical carcinoma HeLa, breast adenocarcinoma MCF7, lung carcinoma A549, and osteocarcinoma U2OS cells." (PMID 31562368, 2020). "Following this lead, we determined the levels of SAG and RBX1 in comparison with those of three F-box proteins in multiple lung cancer cell lines and found in general that the levels of SAG, but not of its family member RBX1, is correlated in an inverse manner with the levels of β-TrCP1 only." (PMID 27910872, 2016).
liver cancer (6 papers, 2021 to 2023). An epithelial or non-epithelial malignant neoplasm that arises from the liver. "Jia and co-workers found that knockdown of RBX1 suppressed the proliferation of liver cancer cells via inducing autophagy and p21-dependent senescence." (PMID 37771770, 2023). "Furthermore, both CUL2 and RBX1 have been shown to contribute to the ubiquitination and degradation of the tumour suppressor RHOB in liver cancer." (PMID 35664333, 2022).
prostate carcinoma (6 papers, 2016 to 2025). A carcinoma that arises from epithelial cells of the prostate gland. "Therefore, RBX1 may be a therapeutic target for metastatic castration-resistant prostate cancer with heterozygous 17p deletion." (PMID 38407310, 2024). "Supporting the relevance of this mechanism, TCGA prostate cancer data show an inverse correlation between RBX1 and POLR2A expression (R = −0.45), suggesting that the loss of POLR2A in cells with deletion of the 17p chromosomal region may be functionally compensated by RBX1 upregulation." (PMID 41487511, 2025). "It is also worth noting that the effect of SAG knockdown appears not to be compensated by RBX1 in prostate cancer cells." (PMID 27955654, 2016).
breast carcinoma (5 papers, 2014 to 2022). "Further, we study the role of RBX1 in metastatic breast cancer in UALCAN database, the findings displayed that in contrast to breast cancer tissues, metastatic breast cancer has an evidently high expression of RBX1." (PMID 35802537, 2022). "After OVCA, the highest frequency of CNL affecting RBX1 was observed in breast cancer (BRCA), at 45.5%, while other gynecological tumors, such as uterine corpus endometrial carcinoma (UCEC), showed RBX1 CNL in only 17.05% of cases." (PMID 25114896, 2014). "RBX1 and RBX2 were the high-risk genes in breast cancer (RFS)." (PMID 36059474, 2022). "We went on to validate the gene expression of the ECV complex genes RBX1, CUL2, TCEB1, and TCEB2 in MCF7 and MDA-MB-231 breast cancer cell lines ectopically overexpressing ∆Np73, and found their downregulation to be consistent with the breast cancer patient data." (PMID 29628507, 2018).
gastric cancer (5 papers, 2016 to 2025). A primary or metastatic malignant neoplasm involving the stomach. "RBX1 also functions to promote the proliferation of gastric cancer cells, and RBX1 expression correlates with a poor prognosis." (PMID 34281459, 2021). "Yet another study examining miR-194's role in preventing the progression of gastric cancer suggested that it was miR-194's regulation of the protein RBX1 that was responsible for its inhibitory effect." (PMID 26909612, 2016). "Similarly, miR-194 regulates the growth and invasion of gastric cancer cells through RBX1." (PMID 34281459, 2021). "CircDIDO1 downregulation leads to a decrease in the RING box protein-1 (RBX1)-mediated ubiquitination and degradation of PRDX2, thereby stabilizing PRDX2 protein and enhancing the antioxidant capacity of gastric cancer cells." (PMID 40227215, 2025). "Given that there is no previous study showing any potential correlation between RBX1/SAG expression and MLN4924 sensitivity, we chose two gastric cancer lines, AGS and SGC-7901 with an over-expressed RBX1 and SAG for this study." (PMID 27063292, 2016). "To further investigate the role of CRL1/SCF in gastric cancer, we first determined the expression levels of three CRL1/SCF E3 components, RBX1, SAG/RBX2 and cullin-1 in several gastric cancer cell lines." (PMID 27063292, 2016). "Taken together, these results showed that two RING components of CRL1, RBX1 and SAG are over-expressed in a number of gastric cancer cell lines and that MLN4924 effectively inactivates cullin neddylation." (PMID 27063292, 2016). "Compared to the levels in immortalized “normal” human gastric epithelial GES-1 cells, RBX1 and SAG were over-expressed in most of gastric cancer cell lines tested, with the highest expression seen in MKN-45, AGS and SGC-7901 cells." (PMID 27063292, 2016).
myeloma (5 papers, 2023 to 2025). "RBX1, an E3 ubiquitin ligase activator, reportedly promoted cell cycle progression in melanoma and multiple myeloma cell lines, since lentiviral vector‐mediated overexpression enhanced progression into the S phase." (PMID 40022573, 2025). "Herein, RBX1 silencing in MM cells inhibited cell proliferation and induced multidrug resistance, providing direct evidence for the crucial role of RBX1 in myeloma progression." (PMID 37639640, 2023). "First, we showed that the RBX1 protein was significantly reduced upon myeloma cell adherence to the stromal cell line HS-5." (PMID 37639640, 2023). "The overexpression of RBX1 using a lentivirus vector inhibited cell adhesion-dependent p27 elevation and induced myeloma cell proliferation on co-culturing with HS-5." (PMID 37639640, 2023). "Cell growth and apoptosis analyses indicated that the role of RBX1 in regulating myeloma cell proliferation and drug resistance was dependent on p27 accumulation, especially via Thr187 phosphorylation." (PMID 37639640, 2023). "This study, for the first time, clarifies the functional role of RBX1 in myeloma cell survival and drug resistance by investigating RBX1-induced p27-dependent signaling pathways." (PMID 37639640, 2023). "In conclusion, this study demonstrates that RBX1 plays an important role in MM cell growth and survival, providing direct evidence for the crucial role of RBX1 in myeloma multidrug resistance." (PMID 37639640, 2023). "Additionally, cell growth and apoptosis analysis indicated that the role of RBX1 in regulating myeloma cell proliferation and drug resistance resulted from p27 accumulation, which occurred in a Thr187 phosphorylation-dependent manner." (PMID 37639640, 2023). "Notably, the induced expression of RBX1 abolished the cell adhesion-mediated elevation of p27 and shortened its half-life, indicating that RBX1 expression was required for p27 upregulation when myeloma cells were co-cultured with HS-5." (PMID 37639640, 2023). "Thus, it is reasonable to conclude that RBX1 mediates myeloma cell growth and drug resistance through the activity of the ubiquitin ligase." (PMID 37639640, 2023). "Additionally, RBX1 knockdown significantly inhibited myeloma development in SCID-Hu mice and in a human MM xenotransplant model." (PMID 37639640, 2023). "Recently, lenalidomide, a CRBN/RBX1 inhibitor, has shown protective roles in multiple COVID-19–infected myeloma patients against progression into severe infections, which suggests the emergence of this particular platelet subpopulation may drive the disease severity in COVID-19 infection." (PMID 41066207, 2025). "Recently, Lenalidomide, a CRBN/RBX1 inhibitor, has shown protective roles in multiple COVID-19 infected myeloma patients against progressing into severe infections, and suggests the emergence of this particular platelet subpopulation may drive the disease severity in COVID-19 infection." (PMID 39764102, 2024). "In the application of DrugFormer to the scRNA‐seq data of multiple myeloma, we unveiled a specific cancer cell state exhibiting stronger drug resistance while presenting elevated expressions of FEN1, RBX1, and COX8A." (PMID 39206872, 2024). "Additionally, the direct activation of the RBX1-p27 axis could be a potential central molecular mechanism by which RBX1 exerts its proapoptotic activity in chemotherapeutics-treated MM cells and adherent myeloma cells." (PMID 37639640, 2023). "A strong negative correlation was observed between p27 and RBX1 levels when myeloma cells were co-cultured with HS-5." (PMID 37639640, 2023).